IL1B (interleukin 1 beta)
Diseases named in the same sentence as IL1B in open-access papers (continued):
Sharing a sentence is not in itself a finding about the gene and the disease.
atherosclerosis (continued). "Evidence suggests that interleukin (IL)-1β is important in the pathogenesis of atherosclerosis and its complications and that inhibiting IL-1β may favorably affect vascular disease progression." (PMID 27737744, 2016). "Dapagliflozin may be of therapeutic potential for diabetic atherosclerosis induced by high-fat diet, and these benefits may depend on the inhibitory effect on the secretion of IL-1β by macrophages via the ROS-NLRP3-caspase-1 pathway." (PMID 28104929, 2016). "Therefore, given the key role for IL-1β as a mediator of innate immunity and the effects of interleukin inhibition in experimental atherosclerosis, interventions to reduce inflammation through IL-1β have been proposed to treat atherosclerosis." (PMID 27737744, 2016). "Data from preclinical studies have suggested that inhibiting IL-1β may directly affect atherosclerosis and vascular inflammation." (PMID 27737744, 2016). "Although chronic inflammation and NLRP3 inflammasome activation have been implicated in atherosclerosis and fatty liver disease, whether SREBP-1c is involved in regulating NLRP3 and IL-1β expression in HGFs remains largely unknown." (PMID 28083517, 2016). "In addition, the S1P receptor S1P2 regulates vascular inflammation and atherosclerosis by inducing the release of inflammatory cytokines IL-1β and IL-18 and retaining macrophages in plaques." (PMID 27711202, 2016). "Human monocytes exhibit dysregulated inflammatory responses with aging consisting of both elevated (i.e. increased TNF‐α) and impaired (i.e. decreased IL‐1β) responses, both of which could contribute to atherosclerosis." (PMID 27135421, 2016). "Therefore, IL-1β is easier to detect and is thought to be more relevant to atherosclerosis-related inflammation." (PMID 26098632, 2015). "P2X7R may also modulate the release of several cytokines known to promote atherosclerosis, including interleukin (IL)-1β, IL-6 and tumor necrosis factor α through immune cells." (PMID 25761252, 2015). "PDTC also remarkably reduced atherosclerosis and the levels of IL-1β, TNF-α and MCP-1 in plasma." (PMID 25860573, 2015). "In addition to inducing foam cell formation, ox-LDL can activate macrophages to produce proinflammatory cytokines, such as TNF-α, IL-6, and IL-1β, to promote atherosclerosis." (PMID 26045945, 2015). "The IL-1β-induced inflammation-activated endothelial cell (EC)-smooth muscle cell (SMC)-mononuclear cell (MC) co-culture model was established, based on the changes in a series of atherosclerosis-associated inflammatory markers secreted by ECs and SMCs." (PMID 25936371, 2015). "It should also be noted that cancer cells are well known to secrete pro-inflammatory cytokines such as TNF-α, IL-6, and IL-1β; all of which act to promote a local, pro-neoplastic environment (which may also influence atherosclerosis)." (PMID 26000958, 2015). "In our study, Homer1, like TNF-α and IL-1β, could be a potential and important participant in diagnosing early atherosclerosis, consequently, CAD." (PMID 25551602, 2014). "Inflammatory cytokines such as Tumor necrosis factor-α (TNF-α), IL-1β and IL- 6 were found to play a central role in the vicious circle of inflammation, endothelial dysfunction and atherosclerosis in patients with diabetic micro and macrovascular complications." (PMID 24822086, 2014). "The example of GM-CSF mediated induction of IL-1β, a known mediator of atherosclerosis, provides an illustration of how CX3CL1 and GM-CSF may have multiple downstream effects to augment atherosclerosis." (PMID 24995121, 2014). "The reduced IL1β may have contributed to the reduced atherosclerosis, given that a genetic deletion of IL1β decreases the severity of atherosclerosis in ApoE−/− mice." (PMID 23560095, 2013). "These preclinical studies provide biochemical evidence that the dysregulation of SIRT1-AMPK-SREBP pathway and stimulation of NLRP3 inflammasome and IL-1β production may coordinately contribute to the initiation and progression of atherosclerosis." (PMID 23825667, 2013).
atherosclerosis (continued). "The reductions in TNFα and IFNγ may also have contributed to the reduced atherosclerosis IL1β and TNFα enhance macrophage-derived foam cell formation by inhibiting macrophage intracellular lipid catabolism." (PMID 23560095, 2013). "The trigger of this proposed pathway may be a specific response to IL1B, or part of a general inflammatory response, such as is known to occur in early atherosclerosis and diabetes." (PMID 24086293, 2013). "The intracellular apparatus consisting of NLRP3, ASC, and caspase-1 all cooperate to drive the generation and subsequent release of active IL-1β and IL-18 by macrophages in response to cholesterol crystals and play an important role in the development of atherosclerosis." (PMID 23401644, 2013). "Therefore, the balance between IL-1β and IL-1Ra is thought to contribute to the pathogenesis of atherosclerosis." (PMID 23029154, 2012). "In addition to these findings, blockade of IL-1β decreased the severity of atherosclerosis and insulin sensitivity in animal models." (PMID 21274430, 2010). "Interleukin (IL)-1β is a potent proinflammatory cytokine markedly overexpressed in the brains of patients with Alzheimer's disease (AD), and also involved in development of atherosclerosis and coronary artery disease." (PMID 20184726, 2010). "Tumor necrosis factor (TNF) receptor-associated factors (TRAFs) are intracellular adaptor proteins, which channel signaling for members of the TNF-/interleukin-1 (IL-1)-/toll-like-receptor (TLR)-superfamily such as TNFα, CD40L, and IL-1β, proteins known to promote inflammation and atherosclerosis." (PMID 20644648, 2010). "Increasing evidence indicates that IL-1 is involved in both development of atherosclerosis and cardiovascular risk, and CASP1 might play a key role in the proatherogenic effects mediated by IL-1β." (PMID 20184726, 2010). "Additional evidence for its role in atherosclerosis comes from an animal model showing that in apoE-deficient mice a lack of IL-1β is associated with decreased severity of atherosclerosis." (PMID 19347053, 2009). "Additionally, neutrophils can participate in NETosis, resulting in the release of neutrophil extracellular traps (NETs) that enhance macrophage activation and the secretion of proinflammatory cytokines, including IL-1β and IL-18, thereby accelerating the progression of atherosclerosis." (PMID 40643541, 2025). "Therefore, the KGs in the early stages of atherosclerosis are IL1B and AREG." (PMID 40824771, 2025). "Similarly, in a rabbit model of atherosclerosis, supplementation with jaboticaba (P. cauliflora) peel decreased plasma levels of IL-1β, IL-6, and soluble intercellular adhesion molecule-1 (sICAM-1) and soluble vascular cell adhesion molecule-1 (sVCAM-1) and reduced atherosclerotic lesions." (PMID 41375968, 2025). "The absence of IL-1β also significantly alleviates atherosclerosis in apoE-deficient mice." (PMID 41194915, 2025). "In regressing female mice, trehalose mitigated the IL-1β increase back to baseline levels, while plaque IL-1β levels were not significantly different between the groups in male mice, highlighting sex differences in inflammation resolution during atherosclerosis regression." (PMID 38433753, 2024). "Pro-inflammatory cytokines such as IL-1β, IL-6 and TNF-α and anti-inflammatory cytokines such as IL-4 and IL-10 provide further insights into the mediators of cellular and systemic responses and have been linked to causal pathways related to atherosclerosis and thrombosis." (PMID 39767790, 2024). "Consistent with the capacity of HGS stroke serum to induce endothelial dysfunction 1 year after stroke onset, IL-1β levels were significantly elevated at this long-term stage, confirming that the effect of serum is likely associated with atherosclerosis rather than stroke." (PMID 36536168, 2024).
atherosclerosis (continued). "In addition to that, we performed some exploratory studies on phagocytosis and on adhesion to iPSC-derived ECs, which are both key aspects of atherosclerosis pathophysiology We observed that training with IL-1β tends to increase monocyte attachment to iPSC-derived ECs." (PMID 39515317, 2024). "Furthermore, a long-term clinical study indicated that treatment with neutralizing IL-1β-specific antibodies dose-dependently reduced lung cancer incidence and mortality in a large cohort of patients with atherosclerosis with a history of myocardial infarction." (PMID 37932814, 2023). "On one hand, IL-1RA is known to bind to the IL-1 receptor, thereby preventing the binding of both IL-1α and IL-1β, and it has been proposed that inhibiting the IL-1 pathway may prevent the development of various CVDs, including atherosclerosis, MI, and heart failure." (PMID 37941911, 2023). "Inflammation is a hallmark of atherosclerosis, and a recent clinical trial, The Canakinumab Anti-Inflammatory Thrombosis Outcomes Study (CANTOS), for the first time showed in a proof-of-concept trial that inhibiting inflammation using an antibody against Il-1β decreased cardiovascular events." (PMID 37396595, 2023). "Previous studies indicated that IL-1β plays a vital role in the pathophysiology of cardiovascular diseases, indicating that decrease IL-1β expression in smooth muscle cells decreases the production of atherosclerotic inflammatory factors and might prevent the progression of atherosclerosis." (PMID 36791122, 2023). "IL-1β may have a greater impact on atherosclerosis in established plaques." (PMID 37701434, 2023). "In addition, endothelial injury caused by HFD-induced atherosclerosis may enhance the production of ROS in vascular endothelial cells, thereby promoting the secretion of the inflammatory cytokines TNF-α and IL-1β." (PMID 37764856, 2023). "While in atherosclerosis it could be beneficial to inhibit immune cell infiltrations as evident that treatment with anti-IL-1B can provide additional cardio-protective benefits by reducing leukocyte recruitment to the atherosclerotic plaque as well as reducing its size." (PMID 37539090, 2023). "Apart from their role in diabetes mellitus control or in all spectrum heart failure, sodium–glucose cotransporter-2 inhibitors (SGLT2i) may play a role in the atherosclerosis reversal on a mice model by the inhibitory effect on IL-1β through ROS/NLRP3/caspase-1 signaling." (PMID 37600028, 2023). "Therefore, although pravastatin decreased foam cell formation, the unexpected increase of IL-1β secretion could, in fact, be detrimental for other atherosclerosis-relevant cell types, such as endothelial cells." (PMID 35372506, 2022). "Furthermore, SARS-CoV-2 leads to cytokine outburst, including IL-6, IL-1b, IL-2, IL-10, and monocyte chemoattractant protein-1 (MCP-1), which are also associated with vascular dysfunction and vascular disease such as atherosclerosis, abdominal aortic aneurysm, varicose veins and hypertension." (PMID 36211676, 2022). "Studies have revealed that TMAO promoted vascular endothelial cell inflammation and advanced atherosclerosis by increasing the expression of the nuclear-factor kappa B (NF-κB), nucleotide-binding oligomerization domain-like receptor family pyrin domain containing 3, IL-1β, and IL-18." (PMID 35242275, 2022). "In another study, both peptides were also able to attenuate atherosclerosis development in apolipoprotein E-deficient mice by reducing the expression of the proinflammatory cytokines IL-6 and IL-1b and the NF-kB-related genes CD40, LCK, PIK3CG, IL1B, and MAP2K7." (PMID 36297084, 2022). "Moreover, our additional database studies showed that miR-124 and miR-16 could also target Interleukin-1 beta (IL-1β) as one of the potential avenues for targeting inflammation in atherosclerosis." (PMID 36433987, 2022).
atherosclerosis (continued). "In addition, selective small P2X7 inhibitors were developed and may be used to block excessive IL-1β secretion during VTE as it has been suggested for atherosclerosis." (PMID 35528838, 2022). "Therefore, targeting TMAO may help to reduce adverse remodeling in atherosclerosis by preventing EC leakage and infiltration of inflammatory cells as well as reducing IL-1β driven inflammation." (PMID 35600479, 2022). "Therefore, USF1 may be involved in atherosclerosis by regulating the expression of IL-1β, VEGF, TNF-α, and IL-6." (PMID 35783856, 2022). "Additionally, reports suggest that IL‐1β is responsible for inducing atherosclerosis." (PMID 35141476, 2022). "A large clinical study showed that controlling inflammation by blocking IL-1β could suppress atherosclerosis and reduce cardiovascular events; however, subsequent research revealed that IL-1β has atheroprotective effects in mice, which suspended further clinical research." (PMID 35493934, 2022). "Consequently, a possible solution to atherosclerosis might be inhibiting IL-1β’s signal transduction, including IL-1 receptor antagonists, the type 2 IL-1 receptor, and soluble receptors." (PMID 36082127, 2022). "Given that some immunotherapies (e.g., CD20-, EGFR-, IL-1β- or PCSK9-targeting antibodies) were shown to protect from both cancer and atherosclerosis, inflammatory processes and immunity underlying carcinogenesis and atherogenesis may be closely interconnected." (PMID 35097027, 2021). "Here, the protective effect of Anagliptin on IL-1β-induced cellular senescence in vascular smooth muscle cells was evaluated to judge whether Anagliptin possesses promising potential in the management of atherosclerosis." (PMID 34288819, 2021). "The Canakinumab Anti-Inflammatory Thrombosis Outcome Study (CANTOS) was the first landmark trial that validated the inflammatory hypothesis in atherosclerosis, where interleukin-1β (IL-1β) antagonism was shown to decrease major adverse cardiovascular events (MACE) independent of lipid-lowering." (PMID 38551014, 2021). "Notably, Class IIa HDAC inhibitors attenuate inflammation in mouse and human macrophages, stabilize atherosclerotic plaques in mice and limit the expression of inflammatory factors IL‐1β and IL‐6 in monocytes from patients with atherosclerosis, a chronic arterial inflammatory condition." (PMID 34145738, 2021). "Besides, TMAO could induce NLRP3 activation, which promotes IL-18 and IL-1β expression to trigger inflammation, which contributed to the endothelial injury that initiates atherosclerosis." (PMID 34414217, 2021). "Furthermore, activation of NLRP3 inflammasome shown to be associated with development and progression of plaque formation and atherosclerosis through increased production of IL-1β and IL-18, upregulation of MCP-1 and VCAM-1 resulting in increased accumulation of vascular extracellular matrix." (PMID 34829831, 2021). "It was concluded that anti-inflammatory therapy targeting the IL-1β innate immunity pathway with canakinumab led to a significantly lower rate of recurrent cardiovascular events independent of lipid-level lowering, therefore bringing out the importance of inflammation in atherosclerosis." (PMID 33807807, 2021). "Given that atherosclerosis is an inflammatory disease promoted by specific cytokines, such as interleukin (IL)-1β, IL-6, and tumor necrosis factor (TNF)-α, we aimed at evaluating whether sex could affect the levels of these proatherogenic cytokines in a group of healthy adults." (PMID 32485823, 2020). "In addition, they demonstrated that CB-ECFCs were able to decrease the expression of mediators of inflammation and atherosclerosis produced by allogeneic lymphocytes and monocytes (IL-1β, IL-8, PGF, ALOX-5, TNFα, CSF-2, MMP-1, MMP-9) more significantly than adult ECFCs." (PMID 32381102, 2020).
atherosclerosis (continued). "In this study, we provided new evidence that miR-216a was positively correlated with the IL1β expression in carotid atherosclerotic plaques, which could give more accurate information about miR-216a as a biomarker for vascular inflammation and atherosclerosis." (PMID 33282009, 2020). "To determine whether TWIST1 expression could be induced in differentiated SMCs, and therefore be relevant in adult pathology as well as in development, we stimulated cells with interleukin (IL)-1β, an inflammatory cytokine upregulated during atherosclerosis disease progression." (PMID 31917787, 2020). "Furthermore, augmented IL-1β and NLRP3-inflammasome activation was described as a major driver of atherosclerosis in mice with hematopoietic Tet2 deficiency, and pharmacologic inhibition of the inflammasome significantly reduced the proatherogenic effect of Tet2-deficient myeloid cells." (PMID 32825226, 2020). "Compared with the sh-NC group, the levels of IL-1β and TNF-ɑ in the sh-ADAM10 group were significantly decreased (p < 0.05), suggesting that silencing ADAM10 could inhibit the inflammatory response associated with atherosclerosis." (PMID 30926762, 2019). "Here, the inflammatory molecules in our panel that showed the most significance in PD, and particularly IL-1α, IL-1β, IL-17A, and TNF-α are all known to be dysregulated in cardiovascular disease and their presence in circulation might be linked to atherosclerosis." (PMID 31507404, 2019). "It is not yet known how many risk factors in the development of atherosclerosis could be modulated by the genetic variants of IL1B, which acts as a key regulator in inflammatory processes." (PMID 31480765, 2019). "Canakinumab, a fully human IL-1β neutralizing monoclonal antibody, emerged as a potentially more viable candidate both because of the specific role IL-1β signaling plays in potentiating atherosclerosis and because it would leave host immune function via IL-1α intact." (PMID 30873416, 2019). "Thus, IL-1β lies far enough upstream in the inflammation pathway that modulation of these proteins could dramatically impact numerous inflammatory components of atherosclerosis." (PMID 29922680, 2018). "Excitingly, recently published data from the CANTOS study, a randomized trial of the role of IL-1β inhibition in atherosclerosis, suggests that anti-inflammatory therapy targeting the IL-1β pathway could significantly reduce incidence of lung cancer and lung cancer mortality." (PMID 29946544, 2018). "The CANTOS (NCT01327846) clinical trial provided critical evidence that targeting IL1β alone with the monoclonal antibody canakinumab can reduce major cardiovascular events along with proinflammatory cytokines (IL-6) and high sensitivity C reactive protein in patients with atherosclerosis." (PMID 29988570, 2018). "Similarly, silencing IL-1α, IL-1β, and caspase-1 respectively in Apoe−/− mice could attenuate atherosclerosis development." (PMID 29850631, 2018). "NLRP3-dependent secretion of IL-1β is closely linked to numerous non-communicable diseases including haemorrhagic disorders, Alzheimer’s disease, gout, diabetes and atherosclerosis." (PMID 28067797, 2017). "Thus, parallel studies performed in diabetic patients without evidence of advanced vascular lesions would help shedding light on the capacity of canakinumab or other IL-1β blocking drugs to prevent or retard the onset of atherosclerosis or other vascular alterations in the context of DM." (PMID 28659798, 2017). "In addition, PI-PLCγ1, activated by TLR4 stimulation with minimally oxidized LDL, induces ROS generation in macrophages, leading to the production of pro-inflammatory cytokines such as TNF-α, IL-1β and IL-6, all having central roles in the pathogenesis of atherosclerosis." (PMID 28661459, 2017).